ICAM1 (intercellular adhesion molecule 1)
Diseases named in the same sentence as ICAM1 in open-access papers (continued):
Sharing a sentence is not in itself a finding about the gene and the disease.
monocytic leukemia (4 papers, 2009 to 2022). "Soyasaponin A3 and two types of soyasapogenols (B and C) also exhibited anti-inflammatory activities by inhibiting TNFа-induced expression of intercellular adhesion molecule-1 (ICAM-1) in THP-1 human monocytic leukemia cells." (PMID 32493316, 2020). "The U937 cell line is a monocytic leukemia with high ICAM-1 (CD-54 adhesion molecule) expression on the cell surface (left & center)." (PMID 19367337, 2009). "For instance, the addition of M5 protein that adheres explicitly to ICAM-1 and ICAM-4, or siRNA targeting ICAM-1 decreased infection of cultured THP-1 (a human monocytic leukemia cell line) and murine peritoneal macrophages by Mycobacterium tuberculosis." (PMID 35316427, 2022). "Notably, recombinant SlaA induced ICAM1 and VCAM1 expression in human umbilical vein endothelial cells (HUVECs), resulting in enhanced adhesion of human monocytic leukemia (THP-1) cells." (PMID 28713783, 2017).
obstructive sleep apnea (4 papers, 2013 to 2023). "Background and objective: Intercellular adhesion molecule-1 (ICAM-1) appears to be an active and important biomarker for decreasing the risk of cardiovascular issues among individuals with obstructive sleep apnea (OSA)." (PMID 36295659, 2022). "The present study, based on our information, is the first to investigate the relationship between serum biomarkers VCAM-1 and ICAM-1, EFT, and the CVR predicted by SCORE-2 and SCORE-2OP risk tools in patients with obstructive sleep apnea." (PMID 38255155, 2023). "Resistin is significantly correlated with IL-6 and ICAM-1 in patients with obstructive sleep apnea syndrome." (PMID 27549428, 2016).
ovarian tumor (4 papers, 2001 to 2019). "ICAM-1 is an important cell-adhesion molecule directly linked to ovarian tumor growth, metastasis and chemo-resistance." (PMID 28679402, 2017). "We found that intercellular adhesion molecule-1 (ICAM-1) was expressed at lower levels in the ovarian tumour cell lines OAW42, PEO1 and JAM than in the immortalised human ovarian surface epithelial cell line HOSE 17.1." (PMID 11720474, 2001). "There were statistically significant differences among the studied groups (P = 0.001), so ICAM-1 rs1437 SNP could be a good predictor for progression of ovarian tumor." (PMID 27252704, 2016).
Parkinson disease (4 papers, 2021 to 2024). A progressive degenerative disorder of the central nervous system characterized by loss of dopamine producing neurons in the substantia nigra and the presence of Lewy bodies in the substantia nigra and locus coeruleus. "ICAM-1 mediates cellular inflammation and is potentially modulated by DJ-1 and α-synuclein (2 proteins closely linked to Parkinson’s disease), particularly during neurodegenerative processes that extend beyond the regulatory impact on endothelial functions." (PMID 39641002, 2024). "Accordingly, RANTES and ICAM-1 are potential inflammatory biomarkers for detecting Parkinson’s disease." (PMID 39641002, 2024).
posterior uveitis (4 papers, 2016 to 2024). Inflammation of the choroid as well as the retina and vitreous body. "Our previously published work has demonstrated that ICAM-1 blockade reduces human retinal endothelial transmigration of leukocytes implicated in the initiation of non-infectious posterior uveitis: Th1 cells, Th17 cells and B cells." (PMID 38984117, 2024). "Based on published literature implicating transcription factor ETS-1 as an activator of ICAM1 gene transcription, we considered it a promising drug target for blocking the induction of ICAM-1 during non-infectious posterior uveitis." (PMID 38984117, 2024). "Induction of retinal endothelial ICAM-1 is a key event in the development of non-infectious posterior uveitis that is regulated at transcription." (PMID 38984117, 2024). "Intercellular adhesion molecule 1 (ICAM-1) is a central cell adhesion molecule for retinal transendothelial migration of the leukocytes in non-infectious posterior uveitis." (PMID 38984117, 2024). "Intercellular adhesion molecule 1 (ICAM-1) mediates leukocyte migration across the retinal endothelium in noninfectious posterior uveitis." (PMID 27293321, 2016).
prostate tumor (4 papers, 2014 to 2023). "E2F1 knockdown inhibited prostate tumor growth in vitro and in vivo through sensitizing tumor cells to ICAM-1 mediated anti-immunity by NF-κB modulation, highlighting the potential of E2F1 as a therapeutic target." (PMID 24742333, 2014).
psoriatic arthritis (4 papers, 2013 to 2026). Joint inflammation associated with psoriasis. "Inflammation in psoriatic arthritis is primarily mediated by IFN-γ, as it increases MHC-II expression on ICAM-1 on the surfaces of synovial membranes, facilitates inflammatory cytokine production, and causes Th1 dominance while decreasing T suppressor activity." (PMID 34239993, 2021).
renal failure (4 papers, 2020 to 2022). "TNF-α is involved in the progression of renal insufficiency through its cytotoxic and proinflammatory effects, such as by inducing endothelial cells (ECs) to express intercellular adhesion molecule-1 (ICAM)-1." (PMID 34211440, 2021). "We also found that this process reversed the up-regulation of fibronectin (FN) and intercellular adhesion molecule 1 (ICAM-1) and led to an improvement in renal insufficiency." (PMID 33519483, 2020).
retinal detachment (4 papers, 2011 to 2024). An eye emergency condition which may lead to blindness if left untreated. "ICAM-1 has an important role in regulating leukocyte migration into sites of inflammation, thereby enhancing cytokine-mediated inflammatory reactions after retinal detachment." (PMID 21556354, 2011). "Positive correlations were found between the intraocular levels of several cytokines (IL-6, IL-8, MCP-1, ICAM-1, and ANG2) and CRT, NPAs, serous retinal detachment, and ME severity." (PMID 39272767, 2024). "The median levels of the cell adhesion molecule ICAM-1 were significantly elevated in the PVR group as compared to the RRD group (P = 0.002), even after having corrected for differences in preoperative PVR grade, duration of retinal detachment, and macular involvement (P = 0.016)." (PMID 21556354, 2011).
sarcopenia (4 papers, 2023 to 2026). Progressive decline in muscle mass due to aging which results in decreased functional capacity of muscles. "After full adjustment, ICAM‐1 and VCAM‐1 were associated with sarcopenia, low SMI and HGS." (PMID 38644163, 2024). "Among the endothelial biomarkers measured, ICAM‐1 (OR: 2.47/1‐SD increase; 95% CI: 1.62–3.75) and VCAM‐1 (OR: 1.91/1‐SD increase; 95% CI: 1.27–2.87) were independent predictors of sarcopenia." (PMID 38644163, 2024). "This indicates that ICAM‐1 and VCAM‐1 are independent endothelial biomarkers of sarcopenia in CKD." (PMID 38644163, 2024).
septic shock (4 papers, 2009 to 2023). Shock caused by infection; frequently caused by gram negative bacteria, although some cases have been caused by other bacteria, viruses, fungi, and protozoa; characterized by fever, chills, tachycardia, tachypnea, and hypotension. "Weigand and colleagues already described that ICAM-1 may exhibit the ability to predict mortality in septic shock, whereas endotoxin, IL-6, and other different circulating adhesion molecules (e.g. soluble L-selectin, soluble P-selectin, soluble E-selectin) failed to be of prognostic value." (PMID 19538738, 2009).
systemic sclerosis (4 papers, 2004 to 2023). A chronic disorder, possibly autoimmune, marked by excessive production of collagen which results in hardening and thickening of body tissues. "Treatment of activin (100 mg/kg/day) in systemic sclerosis patients for 30 days reduced soluble adhesion molecules (i.e., ICAM-1, VCAM-1, E-selectin) and malondialdehyde (MDA) levels in serum." (PMID 34258301, 2021). "Recently, grape seed proanthocyanidins have been demonstrated to reduce the expression of soluble adhesion molecules, ICAM-1, VCAM-1 and E-selectin in the plasma of systemic sclerosis patients." (PMID 15498105, 2004).
thyroid tumor (4 papers, 2018 to 2024). A benign or malignant neoplasm affecting the thyroid gland. "Combining programmed death 1(PD-1) blockers with CAR-T cells that target ICAM1 enhances the efficacy of eliminating ICAM1-expressing thyroid tumor cells compared to using only CAR-T therapy." (PMID 38911868, 2024).
Ureteral obstruction (4 papers, 2012 to 2024). Obstruction of the flow of urine through the ureter. "By qRT-PCR, we found that the inflammatory markers TNF-α, IL-1β, and ICAM-1 were markedly elevated following 7-day ureteral obstruction, and such increments were robustly abolished or attenuated by rotenone administration." (PMID 25140114, 2014). "In support of this hypothesis, we have recently demonstrated that the inhibition of STAT3 by S3I-201 suppressed the expression of TNF-alpha, IL-1beta, and ICAM-1 without affecting that of MCP-1 in the mouse kidney injured by ureteral obstruction." (PMID 22558380, 2012).
viral myocarditis (4 papers, 2015 to 2023). Myocarditis that is caused by an infection with a viral agent. "Our results from the KEGG pathway analysis for genes in subnetworks revealed that ICAM1 might play roles in viral myocarditis and CAMs and thus contributed to PD." (PMID 29686831, 2018). "The proteins ICAM1 (M3WBF1_FELCA) and CDH17 (M3WMR7_FELCA) were upregulated, while ITGAL (M3 WC52_FELCA) and ITGAE (M3W8N0_FELCA) were downregulated in the viral myocarditis pathway." (PMID 36290246, 2022). "In addition, ICAM1 was involved in six KEGG pathways of subnetwork c, such as viral myocarditis, cell adhesion molecules (CAMs), and NF-κB signaling pathways." (PMID 29686831, 2018).
vivax malaria (4 papers, 2013 to 2021). "Syndecan-1 was also associated with the adhesion molecule ICAM-1 in both knowlesi and vivax malaria." (PMID 33963210, 2021). "Interestingly, our networks revealed the association of soluble CD40L and P-selectin with ICAM-1 and E-selectin, indicating the interplay between these two cell populations in vivax malaria." (PMID 32687542, 2020). "Our findings of increased endothelial activation in severe vivax malaria are consistent with a recent study reporting higher concentrations of ICAM-1 and VCAM-1 in severe compared to uncomplicated vivax malaria." (PMID 25569250, 2015). "Syndecan-1 also correlated with endothelial activation (ICAM-1, angiopoietin-2) and ADMA in vivax malaria." (PMID 33963210, 2021). "It was observed that TNF-α, IL-10, ICAM-1 and VCAM-1 were the 4 best individual predictors of complicated vivax malaria with AUROC of 0.89 (95% CI: 0.84 - 0.94), 0.79 (95%CI: 0.73- to 0.86), 0.63 (0.55-0.71) and 0.84 (95% CI: 0.78- 0.90) respectively." (PMID 24324686, 2013). "The median concentrations of the endothelial adhesion receptors E-selectin and ICAM1 were also increased in severe and non-severe vivax malaria compared to controls (P<0.001 for all comparisons)." (PMID 25569250, 2015).
abdominal aortic aneurysm (3 papers, 2017 to 2024). Enlargement and ballooning of the vessel that supplies arterial blood to the abdomen, pelvis and legs. "TNF-α released by activated monocytes, are found in atherosclerotic plaques and in significantly greater levels in abdominal aortic aneurysm, which can enhance ICAM-1 expression on endothelial cell cultures in vitro." (PMID 28069066, 2017).
Abdominal obesity (3 papers, 2016 to 2023). Excessive fat around the stomach and abdomen. "In model 1, the RR of abdominal obesity with DS was 1.30, 95% CI = 1.04–1.62; with hs-CRP was 1.31, 95% CI = 1.21–1.43; and with ICAM-1 was 0.82, 95% CI = 0.60–1.11 for predicting central obesity in White adults." (PMID 34065158, 2021). "ICAM-1 was significantly higher in boys with low-level HDL-c (p < 0.05) and correlated weakly with HDL-c, while adiponectin levels were significantly lower in girls with central obesity and hypertriglyceridemia." (PMID 37822716, 2023).
acute myeloid leukemia (3 papers, 2013 to 2021). Acute myeloid leukemia (AML) is a group of neoplasms arising from precursor cells committed to the myeloid cell-line differentiation. "Recent studies have shown that HDAC inhibitors also have immune-modulatory properties, such as increasing expression of HLA-DR, ICAM-1 and B7-2 in acute myeloid leukemia cell lines." (PMID 24829753, 2013).
African trypanosomiasis (3 papers, 2015 to 2022). "The key protein was ICAM-1, which participates in the African trypanosomiasis pathway, one of the most important pathways under antioxidant stress." (PMID 35562675, 2022). "SOD may protect TMCs mainly by decreasing the levels of ICAM-1, which participates in African trypanosomiasis inhibiting apoptosis." (PMID 35562675, 2022). "Moreover, ICAM-1 is also the key protein involved in African trypanosomiasis, one of the major KEGG pathways for downregulated DEPs between group S and group H. Hence, we can conclude that SOD may suppress the OS induced by H2O2 by decreasing ICAM-1 levels to reduce the apoptosis of TMCs." (PMID 35562675, 2022).
allergic conjunctivitis (3 papers, 2014 to 2024). "Therapies targeting the ICAM-1/LFA-1 interaction have been shown to have positive effects in several eye diseases such as dry eye disease and allergic conjunctivitis." (PMID 32326657, 2020).
autoimmune hepatitis (3 papers, 2021 to 2023). Hepatitis caused by autoantibodies. "Mirtazapine administered in a mouse model of autoimmune hepatitis induced a decrease in the levels of many pro-inflammatory factors, including ICAM-1 in the liver." (PMID 33945102, 2021).
cardiac arrest (3 papers, 2010 to 2014). Cessation of breathing and/or cardiac function. "Our present study confirms that ischemia–reperfusion injury such as that found in cardiac arrest survivors induces ICAM-1 concentration in both humans and laboratory animals." (PMID 25304549, 2014). "From our data we conclude that mild hypothermia initiated after successful resuscitation from cardiac arrest reduces pro-inflammatory cytokine, IL-10, and ICAM-1 mRNA expression compared to normothermia." (PMID 20158893, 2010).
cataract (3 papers, 2023 to 2026). Partial or complete opacity of the crystalline lens of one or both eyes that decreases visual acuity and eventually results in blindness. "Compared with the ARC group, the levels of CTGF, FOS, CAV1, CYR61, ICAM1, EGR1, and NR4A1 in the anterior capsule of PACG patients with cataracts were upregulated, which was consistent with the sequencing data." (PMID 37131205, 2023).
Chagas disease (3 papers, 2015 to 2025). A parasitic infection caused by Trypanosoma cruzi. "These researchers found that many of these piRNAs, such as hsa_piR_016828 and the novel npiR_17, target genes crucial in the fibrotic and inflammatory processes characteristic of Chagas disease, including ICAM1 and SMAD2." (PMID 41295584, 2025). "Endothelial activation during Chagas disease entails the expression of cell adhesion molecules such as E-selectin, vascular cell adhesion molecule-1 (VCAM-1) and intercellular cell adhesion molecule-1 (ICAM-1) through a mechanism involving NF-κB activation." (PMID 25978361, 2015).
choroidal neovascularization (3 papers, 2014 to 2023). An eye disorder described by the growth of new blood vessels that originate from the choroid through a break in the Bruch membrane into the sub–retinal pigment epithelium (sub-RPE) or subretinal space. "In nAMD, adhesion molecules such as Intercellular Adhesion Molecule 1 (ICAM-1) and Vascular Cell Adhesion Molecule 1 (VCAM-1) have been detected in choroidal neovascularization (CNV) and silencing VCAM-1 mRNA expression could suppress experimental CNV." (PMID 37985993, 2023). "In addition to VEGF, choroidal neovascularization (CNV) involves a number of angiogenic molecules and inflammatory cytokines: interleukin-6 (IL-6), interleukin-8 (IL-8), intercellular adhesion molecule-1 (ICAM-1), and monocyte chemoattractant protein-1 (MCP-1)." (PMID 25110587, 2014).
chronic myelogenous leukemia (3 papers, 2014 to 2024). "Gelatinase B/MMP-9 degrades ICAM-1, down-regulating leukocyte homing and promotes evasion of the immune system by chronic myeloid leukemia cells by solubilizing cell membrane ICAM-1." (PMID 24473089, 2014). "Additionally, XN regulates the anti-angiogenic effects of NF-κB by suppressing the level of MMP-9, VEGF, and ICAM-1 stimulated by TNF in chronic myelogenous leukemia." (PMID 38611849, 2024). "Furthermore, an exosome-mediated enhanced expression of intercellular adhesion molecule 1 (ICAM-1) and vascular cell adhesion molecule 1 (VCAM-1) in human endothelial cells have been described in a model for chronic myelogenous leukemia." (PMID 32998758, 2020).
colon adenocarcinoma (3 papers, 2013 to 2022). "For instance, tumor interstitial fluid from colon adenocarcinoma increases the cell-surface expression levels of ICAM-1 and VCAM-1 in HUVEC cells, and tumor-derived angiogenic factors such as VEGF modulate the expression of such adhesion molecules." (PMID 24376728, 2013). "Already in 1994, it was shown that colon adenocarcinoma cells enhanced the expression of major histocompatibility complex 1 (MHC-1) and intercellular adhesion molecule 1 (ICAM-1) upon butyrate exposure, which makes tumor cells more sensitive to cytotoxic lymphocytes-mediated killing." (PMID 35811951, 2022).
coronary stenosis (3 papers, 2013 to 2019). Narrowing of the coronary artery lumen diameter. "Thus, patients with a GG genotype of rs281432 and rs5498 in the ICAM-1 gene may be more susceptible to coronary stenosis." (PMID 25310099, 2014). "Other univariate analyses show that significant coronary stenosis (above 75%) was related to seven polymorphisms: C667T MTHFR, K469E ICAM1, –1607 1G/2G MMP1, –1612 5A/6A MMP3, K167N LOX-1, –675 4G/5G PAI, and IVS7 FVII." (PMID 23274712, 2013).
ductal breast carcinoma (3 papers, 2007 to 2019). "For example, more intense infiltration of malignant lesions by lymphocytes was observed in specimens of medullary breast carcinoma displaying elevated expression of CD54 (ICAM-1) and CD106 (VCAM-1) as compared with ductal breast carcinoma displaying diminished expression of these CAMs." (PMID 17325703, 2007).
endophthalmitis (3 papers, 2018 to 2025). An infectious process affecting the internal structures of the eye. "In addition to chemokines, induced expression of E-selectin and ICAM-1 cells has been implicated in the infiltration of PMNs during endophthalmitis." (PMID 34869079, 2021). "While the mechanisms of neutrophil infiltration into the eye during endophthalmitis are not completely understood, S. aureus is capable of inducing expression of E-selectin and ICAM1 on macrovascular endothelial cells in a rat model of endophthalmitis." (PMID 29661181, 2018). "The observed elevated levels of adhesion molecules ICAM-1 and VCAM-1 during endophthalmitis corroborate with prior studies, indicating their role in retinal inflammation." (PMID 40512033, 2025).
Epstein-Barr virus infection (3 papers, 2016 to 2022). An infection that is caused by Epstein-Barr virus. "Upregulation of ICAM1 in a mechanism involving NF-қB could inhibit the Epstein-Barr virus infection." (PMID 35012443, 2022).